FTO (FTO alpha-ketoglutarate dependent dioxygenase)
Diseases named in the same sentence as FTO in open-access papers (continued):
Sharing a sentence is not in itself a finding about the gene and the disease.
bladder cancer (39 papers, 2019 to 2025). "Conversely, elevated FTO expression in bladder cancer tissues is associated with improved clinical outcomes and acts as an oncogene, promoting the viability and tumorigenicity of bladder cancer cells." (PMID 40271153, 2025). "This study provides a solid foundation for further validation and development of FTO as diagnostic predictor, prognostic marker, or even therapeutic target for bladder cancer." (PMID 33634966, 2021). "Overall, our findings demonstrate that FTO plays oncogenic roles in the molecular basis of cancer, and they indicate that FTO is a potential diagnostic or prognostic biomarker in bladder cancer." (PMID 33634966, 2021). "Analysis of the clinical characteristics of the patients in cohort 2 indicated that FTO protein expression was closely associated with various clinicopathological features of bladder cancer." (PMID 33634966, 2021). "In summary, our research verified that FTO was highly expressed in bladder cancer and associated with a poor prognosis in bladder cancer patients." (PMID 34725345, 2021). "Here, we confirmed that FTO expression was significantly increased in bladder cancer and was associated with a poor prognosis." (PMID 34725345, 2021). "The key N6-methyladenosine demethylase fat-mass and obesity-associated protein (FTO) is negatively correlated with the overall survival of bladder cancer patients, but the underlying mechanism remains poorly understood." (PMID 33461172, 2021). "Taken together, our work revealed that FTO plays a critical role in bladder cancer and could be a potential diagnostic or prognostic biomarker for this disease." (PMID 34725345, 2021). "Our work revealed that FTO plays a critical role in bladder cancer and could be a potential diagnostic or prognostic biomarker for this disease." (PMID 34725345, 2021). "Moreover, differences in the subtypes (transitional or squamous cell carcinoma) and grades of differentiation, which further the degree of malignancy, in bladder cancer cell lines also may be linked to different FTO expression levels." (PMID 33634966, 2021). "Recent research has revealed that m6A modifications, including METTL3, YTHDF1, and FTO, play a pivotal role in promoting bladder cancer development and drug resistance 15-18." (PMID 40083693, 2025). "For example, FTO overexpression has been shown to promote bladder cancer cell proliferation through the FTO/Mir-576/CDK6 pathway." (PMID 40572597, 2025). "Conversely, FTO plays a positive role in bladder cancer by maintaining STAT3 mRNA stability through decreasing its m6A modification levels." (PMID 40244180, 2025). "FTO enhances bladder cancer cell proliferative capacity and migratory potential by stabilizing STAT3 mRNA through an m6A-mediated mechanism." (PMID 40986143, 2025). "Subsequently, through univariate Cox regression analysis, we identified ALKBH5, FTO, IGF2BP2, and IGF2BP3 as potential risk factors for bladder cancer." (PMID 40083693, 2025). "For instance, in renal cell carcinoma, bladder cancer, breast cancer and leukemia, FTO functions as a tumor promoting factor." (PMID 39268470, 2024). "FTO inhibited the growth of bladder cancer cells by G1 phase arrest and inhibits their migration ability." (PMID 37701836, 2023). "In contrast, others reported that FTO was overexpressed in BC, and the knockdown of FTO inhibited bladder cancer cell proliferation." (PMID 37284313, 2023). "The m6A levels increase as the expression of FTO is lowered in a dismal prognosis of bladder cancer patients." (PMID 37444576, 2023). "The overexpression of FTO in human urinary bladder cancer cell lines (HT-1197 and HT-1376) drastically reduces cell proliferation and invasion capacities while considerably increasing cell apoptosis." (PMID 37444576, 2023). "In bladder cancer, FTO accelerates tumorigenesis by removing m6A modifications and activating the MALAT1/miR-384/MAL2 cascade in MALAT1 mRNA." (PMID 37007161, 2023).
bladder cancer (continued). "In the same year, a study by Zhou found that FTO facilitated bladder cancer progression via the FTO/miR-576/cyclin-dependent kinase 6 (CDK6) axis." (PMID 35628623, 2022). "In bladder cancer tissues, the protein level of FTO was positively correlated with CDK6 and negatively related to miR-576." (PMID 35628623, 2022). "Further mechanism study demonstrated that FTO promoted the tumorigenesis of bladder cancer by suppressing microRNA miR-384 and inducing mal T cell differentiation protein 2 (MAL2) expression." (PMID 35628623, 2022). "The analysis of data from the TCGA database showed that the prognosis of patients with a high expression of FTO was worse (p = 0.0015), and FTO expression was higher in patients with a high stage of bladder cancer." (PMID 35311150, 2022). "Bioinformatic analyses and Western blotting assays showed that FTO was highly expressed in bladder cancer tissues and bladder cancer cells." (PMID 35628623, 2022). "We further confirmed the important role of FTO protein in the biological function of bladder cancer cells by performing in vitro experiments." (PMID 35311150, 2022). "FTO functions as an oncogene in bladder cancer cells, and upon FTO knockdown, the level of m6A enzyme activity in bladder cancer cells was significantly increased, apoptosis was increased, and cell proliferation and cell invasion were reduced." (PMID 35311150, 2022). "FTO overexpression promoted bladder cancer cell proliferation, whereas FTO knockdown inhibited bladder cancer cell proliferation." (PMID 34725345, 2021). "The expression level of FTO mRNA was significantly down-regulated in stageII–IV of bladder cancer tissues compared with the normal controls (p = 0.00025 for stageII, p = 0.047 for stageIII and p = 0.0055 for stageIV)." (PMID 34521394, 2021). "IHC staining indicated that in comparison with normal tissues, FTO protein expression was increased in bladder cancer tissue." (PMID 33634966, 2021). "FTO overexpression in bladder cancer correlated with poor prognosis indicating a potential oncogenic function." (PMID 34683137, 2021). "Although it has been demonstrated to play critical roles in various cancers, there is limited knowledge about the specific mechanism of FTO in the tumor initiation of bladder cancer." (PMID 33634966, 2021). "In the bioinformatic analysis of the GEO database, we detected that both the ALKBH5 and FTO genes were connected with bladder cancer." (PMID 33634966, 2021). "Based on the multivariate analysis, FTO protein expression was identified as an independent predictor (p = 0.033) of bladder cancer." (PMID 33634966, 2021). "From the analysis of the tissues collected from cohort 1, we identified that the mRNA expression of FTO increased by 2.8‐fold in the tumor tissues of patients with bladder cancer compared to their normal tissues (p < 0.001)." (PMID 33634966, 2021). "Bladder tumor tissues had increased FTO expression which correlated with clinical bladder cancer prognosis and outcomes." (PMID 33634966, 2021). "On the other hand, FTO was found to be able to stimulate cell viability and facilitate tumor growth in bladder cancer cells." (PMID 33634966, 2021). "We also demonstrated that FTO promoted bladder cancer cell proliferation via the FTO/miR-576/CDK6 pathways." (PMID 34725345, 2021). "In the majority of bladder cancer cell, an upregulation of FTO expression at both the mRNA and protein levels was shown." (PMID 33634966, 2021). "Taken together, these results indicate that FTO targets CDK6 via the FTO/miR-576/CDK6 pathways in bladder cancer." (PMID 34725345, 2021). "In summary, the FTO gene is identified as an oncogenic gene involved in the tumorigenesis of bladder cancer." (PMID 33634966, 2021). "Identification of the correlation of FTO with bladder cancer was based on both bioinformatics and clinical analysis of tissue samples collected from a cohort of patients at a hospital and microarray data." (PMID 33634966, 2021).
bladder cancer (continued). "To recognize the potential mRNA targets of FTO in bladder cancer cells, we next performed transcriptome‐wide sequencing of FTO regulated m6A (m6A‐seq) and RNA‐seq assays on FTO‐knockdown and control 253J cells." (PMID 33634966, 2021). "The IHC analysis showed that the positive FTO rate was significantly higher in bladder cancer tissues." (PMID 34725345, 2021). "Our study subsequently determined the functions of FTO in bladder cancer both in mammalian cells and xenograft of tumor tissues obtained from mice." (PMID 33634966, 2021). "Through successfully establishing FTO‐knockdown and FTO‐overexpressed human bladder cancer cells, we revealed that FTO is oncogenic, as demonstrated by its ability to stimulate cell viability and tumor growth in bladder cells." (PMID 33634966, 2021). "We initially detected FTO expression in bladder cancer tissues and adjacent tissues using qRT-PCR and western blotting." (PMID 34725345, 2021). "In the present study, the expression of FTO increased in bladder cancer tissues, which was consistent with the results of a study by Tao." (PMID 34725345, 2021). "A high expression of FTO is detected in tumor tissue and is clinically related to the pathological traits of bladder cancer, suggesting that FTO is a potential biomarker for either the diagnosis or clinical prediction of bladder cancer." (PMID 33634966, 2021). "The current study only focuses on the functional roles of FTO in bladder cancer by analyzing cellular viability in vitro and tumor development in vivo." (PMID 33634966, 2021). "The mRNA and protein expression amounts of FTO were quantified in human normal bladder cell and bladder cancer cell lines derived from humans." (PMID 33634966, 2021). "In bladder cancer, it was found that m6A RNA methylation regulators could participate in the malignant progression of bladder cancer, and a risk signature with three selected m6A RNA methylation regulators (FTO, YTHDC1, and WTAP) could serve as a promising prognostic biomarker." (PMID 33628782, 2021). "FTO expression and smoking status (p = 0.0267) and pathologic stage (p = 0.0262) of bladder cancer patients were significantly correlated with each other." (PMID 33634966, 2021). "The present study demonstrated that FTO exhibited an oncogenic role in bladder cancer via regulating the expression of cyclin-dependent kinases (CDK6), which are closely related to the cell cycle." (PMID 34725345, 2021). "We further detected the FTO protein staining in bladder cancer patients of cohort 2 as described in Methods." (PMID 33634966, 2021). "FTO, MALAT1, miR‐384, and MAL2 are all clinically relevant biomarkers in bladder cancer, among which the expression of FTO influences the prognosis of bladder cancer patients." (PMID 33634966, 2021). "FTO plays an oncogenic role in bladder cancer, but few studies have focused on how FTO promotes bladder cancer progression by regulating miRNA synthesis." (PMID 34725345, 2021). "FTO promoted bladder cancer cell proliferation, migration and invasion via the FTO/miR-576/CDK6 pathways in an m6A-dependent manner." (PMID 34725345, 2021). "FTO facilitates the tumorigenesis of bladder cancer through regulating the MALAT/miR‐384/MAL2 axis in m6A RNA modification manner, which ensures the potential of FTO for serving as a diagnostic or prognostic biomarker in bladder cancer." (PMID 33634966, 2021). "Gain‐of‐function and loss‐of‐function assays were conducted in vivo and in vitro to assess the effect of FTO on bladder carcinoma tumor growth and its impact on the bladder carcinoma cell viability." (PMID 33634966, 2021). "Both METTL3 and FTO play crucial roles in carcinogenesis in both bladder cancer and renal cell carcinoma." (PMID 32808488, 2020). "Western blot analysis showed an decrease in FTO expression in bladder cancer cell lines (5637, T24 and TCCSUP) compared with a normal bladder epithelial cell line (SV-HUC-1)." (PMID 32299393, 2020).
bladder cancer (continued). "In conclusion, these findings suggest that down-regulation of FTO plays an oncogenic role in bladder cancer." (PMID 32299393, 2020). "However, studies have indicated a significant decrease in FTO mRNA expression in bladder urothelial carcinoma compared to controls, suggesting an oncogenic role in bladder cancer." (PMID 39723162, 2024). "Interestingly, FTO-mediated demethylation of different regions of bladder cancer mRNA exerted differential expression of various genes." (PMID 37007161, 2023). "Moreover, FTO has been well evidenced to promoted bladder cancer cell proliferation via the FTO/miR-576/CDK6 pathways." (PMID 36614216, 2023). "FTO played an oncogenic role in bladder cancer in an m6A-dependent manner." (PMID 35628623, 2022). "In preliminary studies, we found that the expression levels of the classic proto-oncogenes, IGF2BP1, MYC, LIN28B and STAT3 in bladder cancer T24 cells were higher than those in normal cells, while the expression levels of the tumor suppressor genes FTO and TIA1 were negligible in T24 cells." (PMID 35288535, 2022). "Additionally, the FTO protein level was positively correlated with the expression of the deubiquitinase ubiquitin specific peptidase 18 (USP18) expression in bladder cancer." (PMID 35211409, 2022). "The role of m6A involvement with FTO in bladder cancer had not been reported, and we found that in the TCGA and IMvigor210 cohorts, patients with high FTO expression had a poor prognosis, and the expression of FTO was higher in patients with a higher stage of bladder cancer." (PMID 35311150, 2022). "The combination of FTO targeted regulation and anti-PD-L1 blockers may have great therapeutic potential for reducing the resistance of bladder cancer to immunotherapy." (PMID 35311150, 2022). "We examined the nuclear, cytoplasmic, and overall expression levels of FTO in nine human bladder cancer cell lines: BIU87 cells, 5637 cells, T24 cells, EJ cells, RT4 cells, J82 cells, UM-UC-3 cells, TCCSUP cells, and human bladder epithelial immortalized SV-huv-1 cells." (PMID 35311150, 2022). "Non-responsive patients showed significantly higher FTO expression, suggesting that FTO may play an important role in the anti-PD-L1 treatment of bladder cancer." (PMID 35311150, 2022). "FTO promotes bladder cancer tumor growth via MALAT1/miR‐384/MAL2 axis." (PMID 33634966, 2021). "This indicates that FTO exhibits an oncogenic role via the FTO/miR-576/CDK6 pathways in bladder cancer and could be a potential diagnostic or prognostic biomarker for bladder cancer." (PMID 34725345, 2021). "In addition, the overall survival rate was decreased in the bladder cancer patients with a high FTO expression compared to those with a low FTO expression." (PMID 33634966, 2021). "FTO stimulates tumor growth of bladder cancer through regulating MALAT1 methylation." (PMID 33634966, 2021). "We, here, explored the role of FTO and unraveled the mechanism of its function in bladder cancer." (PMID 33634966, 2021). "Moreover, FTO promotes the tumorigenicity of bladder cancer, specifically stimulating tumor growth in vivo and cellular viability in vitro." (PMID 33634966, 2021). "Together, these data indicated that FTO might play an oncogenic role in bladder cancer as a N6-methyladenosine RNA demethylase." (PMID 33461172, 2021). "Therefore, we have systematically illustrated the oncogenic role of FTO in bladder cancer and its molecular mechanism in the process." (PMID 33634966, 2021). "The expression levels of FTO were significantly higher in bladder cancer tissues." (PMID 34725345, 2021). "We downregulated miR-576 in stable FTO-knockdown T24 and UM-UC-3 cells and demonstrated that the inhibition of miR-576 expression partly restored the decreased proliferation and colony formation abilities of bladder cancer cells." (PMID 34725345, 2021). "Hence, future research on the expression of FTO in different bladder cancer cell lines should be performed." (PMID 33634966, 2021).
bladder cancer (continued). "Moreover, the expression of CDK6 increased significantly in FTO-overexpressing bladder cancer cells and decreased significantly in FTO knockdown bladder cancer cells." (PMID 34725345, 2021). "The role of FTO in bladder cancer (BLCA) has been ill-elucidated thus far." (PMID 33461172, 2021). "The further exploration of regulation of FTO expression may provide us a potential therapeutic target for the treatment of bladder cancer." (PMID 32299393, 2020). "In addition, FTO overexpression in bladder cancer tissues exhibits a significant correlation with aggressive tumor phenotypes and could serve as an independent predictor of clinical outcomes." (PMID 40986143, 2025). "METTL14, YTHDC1, and WTAP may be protective factors for bladder cancer, the higher expressions were related to the longer overall survival of patients, while IGF2BP1-3, YTHDF1, LRPPRC, ALKBH5, and FTO were risk factors for bladder cancer." (PMID 37701836, 2023). "Moreover, FTO stimulated tumor growth of bladder cancer in vivo and in vitro." (PMID 35628623, 2022). "Therefore, FTO may play an important role in the occurrence and development of bladder cancer, the efficacy of anti-PD-L1 immune checkpoint therapy, and might be useful for predicting the prognosis." (PMID 35311150, 2022). "Consequently, we proposed that FTO could be an important molecular biomarker and prognostic indicator of bladder cancer patients." (PMID 33634966, 2021). "Considering that few studies have focused on how FTO promotes tumour formation by regulating miRNA synthesis, our study demonstrated that FTO could promote bladder cancer proliferation via the FTO/miR-576/CDK6 pathway by regulating the maturation of primiR-576 in an m6A-dependent manner." (PMID 34725345, 2021). "Patients with bladder cancer exhibiting high FTO levels may have a worse prognosis." (PMID 34725345, 2021). "Therefore, the different levels of the Akt/SP1 signaling axis in bladder cancer cell lines may contribute to different FTO expression levels." (PMID 33634966, 2021). "In addition, decreased FTO takes a tumorigenic role in bladder cancer 32 and a highly selective inhibitor of FTO could restrain the cisplatin-induced cytotoxicity in bladder cancer cells." (PMID 34149936, 2021). "We demonstrate that the mechanism underlying the oncogenic effect of FTO is based on its capability of MALAT1 demethylation and the regulatory functions on the MALAT/miR‐384/MAL2 axis, which are three of the crucial molecular biomarkers clinically relevant to bladder cancer." (PMID 33634966, 2021). "Mechanistically, FTO modifies m6A RNA to regulate the MALAT1/miR-384/MAL2 axis, accelerating bladder cancer development." (PMID 40271153, 2025). "The differential dependency of FTO and ALKBH5 in the same tumor context has also been reported in bladder cancer and B cell lymphoma." (PMID 40435251, 2025). "As a result, FTO decreased N6-methyladenosine methylation level in PYCR1 through its demethylase enzymatic activity and stabilized PYCR1 transcript to promote bladder cancer initiation and progression." (PMID 33461172, 2021). "P < 0.1 as the reference standard, we found that three genes were correlated with the prognosis of bladder cancer, namely YTHDC1, FTO, WTAP." (PMID 34521394, 2021). "We analyzed the RNA-Seq data for YTHDC1, FTO and WTAP in different stages (TNM) of bladder cancer samples from TCGA (412 bladder cancer and 19 normal samples)." (PMID 34521394, 2021). "We found that three genes were correlated with the prognosis of bladder cancer, namely YTHDC1, FTO, WTAP." (PMID 34521394, 2021). "Our work shows the importance of N6-methyladenosine RNA modification in bladder cancer development, and highlights UPS18/FTO/PYCR1 signaling network as potential therapeutic targets of bladder cancer." (PMID 33461172, 2021).